CPT1A (carnitine palmitoyltransferase 1A)
Diseases named in the same sentence as CPT1A in open-access papers (continued):
Sharing a sentence is not in itself a finding about the gene and the disease.
liver fibrosis (8 papers, 2022 to 2026). "The progression of fibrosis can be mitigated through genetic suppression, pharmacological inhibition of CPT1A, and HSC-specific knockdown of CPT1A in mice with choline-deficient models of liver fibrosis." (PMID 39897543, 2025). "Given that previous studies have shown that CPT1A is highly expressed during the pathological process of liver fibrosis, we further explored the relationship between high expression of CPT1A and the inhibition of HSCs viability after DATs treatment." (PMID 40213908, 2025). "Recently, it has been reported that CPT1A was overexpressed in hepatic stellate cells from patients with liver fibrosis, correlating positively with fibrosis and NAFLD activity score." (PMID 37107193, 2023). "In agreement with this literature data reported up-regulation of FASN genes in several hepatic fibrosis animal models, and our results indicate an up-regulation of Cpt1a and FASN genes." (PMID 36579532, 2022). "Firstly, we examined the expression of CPT1a, since it is a key rate-limiting enzyme of mitochondrial FAO and is involved in kidney and liver fibrosis." (PMID 35568871, 2022). "CPT1a is a key rate-limiting enzyme of mitochondrial FAO and is reported to be involved in fibrotic diseases, such as kidney and liver fibrosis." (PMID 35568871, 2022). "Liver HSCs significantly enhance the activity of carnitine palmitoyltransferase 1A (CPT1A), the rate-limiting enzyme in the β-oxidation of medium- and long-chain fatty acids, in both human and murine models of CCl4-induced and metabolism-driven liver fibrosis." (PMID 39897543, 2025).
Sepsis (8 papers, 2016 to 2025). Sepsis is defined as life-threatening organ dysfunction caused by a dysregulated host response to infection. "USP50 plays a role in aggravating sepsis by stabilizing carnitine palmitoyltransferase 1a (CPT1a) and enhancing FAO." (PMID 38322269, 2024). "CPT1A also seems to drive an anti-inflammatory phenotype, as deletion of CPT1A resulted in increased lung damage in a murine LPS-induced sepsis model while inducing CPT1A expression in the RAW264.7 macrophage cell line reduced expression of iNOS and impaired phagocytotic capacity." (PMID 41235226, 2025). "Therefore, in this study, we utilized inducible mitochondrial STAT3 knock-in mice and discovered that following treatment with LPS, mitochondrial STAT3 exacerbated sepsis along with an increase in FAO via the stabilization of CPT1a." (PMID 34976224, 2022). "For instance, mitochondrial STAT3 can trigger fatty acid oxidation by inducing the stabilization of CPT1a mediated by USP50 in macrophages, exacerbating LPS-induced sepsis." (PMID 40766066, 2025). "In contrast, in sepsis, TGF-β suppresses carnitine palmitoyl transferase 1A (CPT1A)-dependent fatty acid oxidation (FAO), leading to mitochondrial fragmentation and a subsequent loss of cytotoxicity." (PMID 41429765, 2025). "Regulating import of long-chain FAs into the mitochondrial matrix, we found increased CPT1a or b, dependent on the model, along with CPT2 induction in human sepsis." (PMID 35013270, 2022). "For instance, in lipopolysaccharide-induced sepsis, signal transducer and activator of transcription 3 (STAT3) expression was found to be upregulated, which inhibited the ubiquitination of CPT1A produced by macrophages, stabilizing CPT1A expression under the mediation of USP50." (PMID 41219902, 2025). "However, changes in the expression of CPT-1A in the liver during sepsis are not clear." (PMID 27110821, 2016).
clear cell renal carcinoma (7 papers, 2020 to 2025). A malignant epithelial neoplasm of the kidney characterized by the presence of lipid-containing clear cells within a vascular network. "Finally, four genes, including CPT1A, were used to establish a prognostic risk signature in patients with renal clear cell carcinoma." (PMID 33381539, 2020). "Conversely, in clear cell renal carcinoma models, CPT1A inhibition enhances proliferation while its overexpression suppresses proliferation." (PMID 41378259, 2025). "A study showed that overexpression of CPT1A mitigated lipid accumulation and cholesterol uptake in clear-cell renal carcinoma (ccRCC)." (PMID 38397050, 2024). "Weakened CPT1A expression is critical for lipid accumulation to promote clear cell renal carcinoma development." (PMID 38844980, 2024). "Activating the PPARα/CPT1A axis alleviates lipid accumulation and inhibits cell proliferation and migration of clear cell renal cell carcinoma." (PMID 38844980, 2024). "HIF-1 drives lipid deposition by suppressing carnitine palmitoyltransferase 1 A (CPT1A) to promote tumor growth in clear cell renal cell carcinoma." (PMID 39343971, 2024). "CPT1A demonstrated significantly lower expression in renal clear cell carcinoma tissue than in normal renal tissue." (PMID 33381539, 2020). "Using data from the TCGA database, we observed that the expression of CPT1A in renal clear cell carcinoma tissue was significantly lower than that in normal kidney tissue (P = 8.057e − 21)." (PMID 33381539, 2020). "Interestingly, we observed that MED15 deficiency upregulated CPT1A, a key HIF target gene and fatty acid oxidation enzyme known to be suppressed by HIF in renal clear cell carcinoma." (PMID 39947475, 2025). "To investigate whether CPT1A affects the migration and invasion abilities of renal clear cell carcinoma cells, we performed wound healing and Transwell invasion experiments in 786-O and ACHN cell lines." (PMID 33381539, 2020). "In addition, the overexpression of CPT1A may reduce the proliferation, migration, and invasion of renal clear cell carcinoma cells in vitro." (PMID 33381539, 2020). "However, recent research seems to imply that CPT1A may play a different role in renal clear cell carcinoma compared to that in other tumors." (PMID 33381539, 2020). "Therefore, our research focused on exploring the expression and clinical significance of CPT1A in renal clear cell carcinoma, studying the biological effects of CPT1A on renal clear cell carcinoma cells, and using a number of biological methods to explore the mechanism underlying these effects." (PMID 33381539, 2020). "Interestingly, hypoxia was shown to inhibit carnitine palmitoyltransferase 1A (CPT1A) and thus beta-oxidation, which resulted in the accumulation of lipids in form of stored droplets in clear cell renal cell carcinoma." (PMID 35158820, 2022). "In addition, the potential molecular mechanism of CPT1A in the inhibition of renal clear cell carcinoma has not been elucidated completely." (PMID 33381539, 2020). "However, research on CPT1A in renal clear cell carcinoma is still lacking." (PMID 33381539, 2020).
Cognitive impairment (7 papers, 2021 to 2026). Abnormal cognition is characterized by deficits in thinking, reasoning, or remembering. "Here, we show that knockout of carnitine-palmitoyl transferase-1A (CPT1A)—a key enzyme of mitochondrial fatty acid oxidation—in adult mouse astrocytes causes cognitive impairment." (PMID 37460843, 2023). "In ROSMAP, higher levels of brain DNA methylation at the same two CPT1A markers were associated with greater risk of cognitive impairment (P = 0.005 and P = 0.02) and higher AD-related indices (CERAD score: P = 5 × 10−4 and 0.001; Braak stage: P = 0.004 and P = 0.01)." (PMID 37891690, 2023). "A recent study demonstrated that astrocyte-specific deletion of carnitine-palmitoyl transferase-1A (CPT1A), a key enzyme in mitochondrial FAs oxidation, leads to cognitive impairment in mice." (PMID 38419654, 2024). "Hence, the downregulation of CPT1A, which entails decreased activity, appears to be accompanied by increased resistance to the development of cognitive impairment." (PMID 36681683, 2023).
liver cancer (7 papers, 2011 to 2026). An epithelial or non-epithelial malignant neoplasm that arises from the liver. "In conclusion, OA exerts its anti-lipid metabolism effects in HCC by modulating the PPARα-CPT1A axis, indicating its potential therapeutic value in liver cancer treatment." (PMID 42196572, 2026). "Our results uncover a mechanism through which ANGPTL3 reduces SNAI1/CPT1A expression, thereby suppressing tumor metastasis and drug resistance in liver cancer." (PMID 39708716, 2025). "This is the first evidence that ANGPTL3 regulates CPT1A protein stability in sorafenib-resistant liver cancer cell lines." (PMID 39708716, 2025). "Previous results indicated that overexpression of miR-328-3p suppresses the metastasis of liver cancer by regulating CPT1A." (PMID 34045663, 2022). "ANGPTL3 increases sorafenib sensitivity by inhibition of SNAI1 and CPT1A in liver cancer." (PMID 41562091, 2025). "Targeting ANGPTL3/SNAI1/CPT1A axis may serve as a therapeutic approach to improve prognosis of liver cancer patients with sorafenib resistance." (PMID 39708716, 2025).
lung fibrosis (7 papers, 2022 to 2025). "Collectively, our data demonstrate that in vivo deficiency of Cpt1a in AT2 cells leads to a higher susceptibility to developing lung fibrosis after injury." (PMID 39927460, 2025). "In vivo Cpt1a loss in AT2 cells increases susceptibility to lung fibrosis after injury." (PMID 39927460, 2025). "Furthermore, mice with deficiency of CPT1a in AT2 cells show enhanced susceptibility to developing lung fibrosis with an accumulation of epithelial cells expressing markers of intermediate cells, airway secretory cells, and senescence." (PMID 39927460, 2025). "By inhibiting CPT1a expression, increased mitochondrial ROS accelerates the progression of pulmonary fibrosis; however, restoring CPT1a expression impedes pulmonary fibrosis." (PMID 37033923, 2023). "Consistently, the induction of APN/CPT1A signaling limits pulmonary fibrosis in a rat model of pulmonary fibrosis." (PMID 37681924, 2023). "Based on the findings above, we aim to explore the critical role of APN/CPT1A in pulmonary fibrosis and to make an in-depth research on the regulatory mechanism underlying hypoxia-mediated pulmonary fibrosis." (PMID 36035217, 2022). "Consistently, CPT1A overexpression exerted a protective role against pulmonary fibrosis in vivo; however, the antifibrosis property of CPT1A was partly abolished by 3-methyladenine (an autophagy inhibitor)." (PMID 36035217, 2022). "In the present study, we uncovered a critical function for APN/CPT1A-mediated lipid acid metabolism in the development of pulmonary fibrosis." (PMID 36035217, 2022). "Our prior data showed that MCU reprogrammed lung macrophage metabolism to FAO during bleomycin-induced lung fibrosis, in part, by increasing and stabilizing Cpt1a expression and activity." (PMID 34413485, 2022). "In summary, we demonstrated not only that hypoxia-induced macrophage polarization to M1 could induce pulmonary fibrosis but also that the activation of APN/CPT1A-mediated fatty acid metabolism suppressed lipid peroxide accumulation and fibroblast proliferation but activated autophagy in IPF." (PMID 36035217, 2022). "Hence, whether APN/CPT1A-mediated fatty acid metabolism is involved in hypoxia-induced pulmonary fibrosis also deserves to be explored." (PMID 36035217, 2022). "Previous data revealed that carnitine palmitoyltransferase 1A (CPT1A), the rate-limiting enzyme in FAO, was increased in lung macrophages from individuals with idiopathic pulmonary fibrosis." (PMID 40208691, 2025). "In conclusion, these data suggested that HMGCS2 facilitated lipid metabolism of AECIIs through interacting with PPARα, which promoted the expression of CPT1A and CPT2 in mice lung fibrosis models." (PMID 38658970, 2024). "In conclusion, these data suggested that HMGCS2 facilitated lipid metabolic of AECIIs through interacting with PPARα to promote the expression of CPT1A and CPT2 in mice lung fibrosis models." (PMID 38658970, 2024). "A dysregulated CPT1A activity was discovered in lung macrophages from IPF patients, indicating a critical role of CPT1A in pulmonary fibrosis." (PMID 36035217, 2022). "Next, to further explore the regulatory role of fatty acid metabolism during the progression of pulmonary fibrosis, particularly to the induction of macrophages, APN/CPT1A signaling was activated to modulate fatty acid metabolism in HFL-1 cells with the coculture of M1 macrophages." (PMID 36035217, 2022). "Genetic and pharmacological disruption of carnitine palmitoyltransferase 1a (CPT1a) modulates in vitro and in vivo AT2 differentiation by promoting accumulation of aberrant basaloid and airway secretory intermediate cells and reducing the resistance to developing lung fibrosis after injury." (PMID 39927460, 2025). "Therefore, we assumed that HMGCS2 might act as a transcriptional coactivator of PPARα in regulating the expression of PPARα target genes such as CPT1A and CPT2 in lung fibrosis." (PMID 38658970, 2024).
lung fibrosis (continued). "Furthermore, HMGCS2 could increase the expression of CPT1A and CPT2 in lung fibrosis models in mice." (PMID 38658970, 2024). "Furthermore, HMGCS2 could increase the expression of CPT1A and CPT2 in mice with lung fibrosis." (PMID 38658970, 2024).
cervical cancer (6 papers, 2020 to 2026). A primary or metastatic malignant neoplasm involving the cervix. "This study put forward an idea that TM7SF2-induced lipid reprogramming promotes proliferation and migration via CPT1A/Wnt/β-Catenin axis in cervical cancer, underlying the progression of cervical cancer." (PMID 38693136, 2024). "The mechanism and underlying signaling pathway of TM7SF2 via CPT1A associated lipid metabolism in cervical cancer development were explored using Western blotting, IHC, colony formation, transwell assay, and wound healing assay." (PMID 38693136, 2024). "Quantitative real-time PCR and Western blot were used to detect the expression levels of CPT1A in cervical cancer cell lines." (PMID 42072286, 2026). "After incubated with Etomoxir with concentration of 50 μM for 48 h, the protein expression of CPT1A in cervical cancer SiHa and C33A cells was inhibited." (PMID 38693136, 2024). "Compared to the control cervical cancer cells, the enhanced fatty acids were detected in CPT1A-slience SiHa and C33A cells." (PMID 38693136, 2024). "The proliferation and migration of cervical cancer cells were reversed in CPT1A-overexpressed cells with the treatment of MSAB, an inhibitor of Wnt/β-Catenin pathway." (PMID 38693136, 2024). "Crucially, our research identified a central role for TM7SF2 in mediating CPT1A’s function in cervical cancer." (PMID 38693136, 2024). "To gain insights into the underlying mechanisms of TM7SF2 in cervical cancer, we conducted a GSEA analysis, which revealed a significant association between CPT1A and the WNT signaling pathway." (PMID 38693136, 2024). "Firstly, the protein level of CPT1A was compared in cervical cancer tissues and normal cervix tissues using IHC assay, which revealed a significant increase of CPT1A protein expression in cervical cancer tissues, primarily localized in cytoplasm." (PMID 38693136, 2024). "The data demonstrated significant downregulation of GSK3β and upregulation of PKM2 and CPT1A in cervical carcinoma and precancerous lesions compared with NCs." (PMID 31465717, 2020). "Moreover, TM7SF2 directly bonded with CPT1A, a key enzyme in fatty acid oxidation, and regulated CPT1A protein expression in cervical cancer cells." (PMID 38693136, 2024). "Moreover, how CPT1A influenced the biological functions including cell viability and migration in cervical cancer was investigated." (PMID 38693136, 2024). "Then, the aspect of CPT1A on cell migration was further studied in cervical cancer cells." (PMID 38693136, 2024). "A CCK-8 assay was conducted to investigate CPT1A whether it affected cervical cancer cell viability in CPT1A-overexpressed SiHa and C33A cells." (PMID 38693136, 2024). "In addition, to ascertain the function of CPT1A knockdown on fatty acids accumulation of cervical cancer cells, CPT1A-slience SiHa and C33A cells were verified via Western blotting." (PMID 38693136, 2024). "Cervical cancer cell viability was promoted in both cell lines by upregulating CPT1A." (PMID 38693136, 2024). "The miR-532-5p could drives nodal metastasis of cervical cancer through CPT1A-mediated lipid droplet accumulation." (PMID 38844980, 2024). "Notably, the proliferation and metastasis of cervical cancer cells were elevated when their CPT1A expression was upregulated." (PMID 38693136, 2024). "The level of CPT1A in HPV16-positive CC tissues was reported to be markedly higher than that in normal tissues, suggesting that CPT1A could promote cervical cancer progression through lipid metabolism modifications." (PMID 37056351, 2023). "Therefore, the observed increase in expression of CPT1A in cervical carcinoma and precancerous lesions indicates the involvement of CPT1A in lipid metabolism modifications and tumor progression." (PMID 31465717, 2020).
cervical cancer (continued). "Moreover, the data from Transwell migration analysis confirmed that CPT1A overexpression significantly promoted cell migration in SiHa and C33A cells comparing with the corresponding control groups, which suggested that CPT1A regulated the cervical cancer cell proliferation and migration." (PMID 38693136, 2024). "To further investigate the role of FOXK2 in regulating lipid metabolism in a cervical cancer mouse model, we assessed the expression levels of ACC1, FASN, and CPT1A in tumor tissues." (PMID 40641601, 2025). "In cervical cancer cells, we utilized immunofluorescence experiments and discovered that the knockdown of FOXK2 led to a reduction in the expression level of CPT1A, whereas the expression levels of FASN and ACC1 increased." (PMID 40641601, 2025). "Intend to explore the role of CPT1A in regulation of the WNT/β-catenin pathway, the inhibitor of WNT/β-catenin was used in CPT1A-overexpressed cervical cancer cell lines." (PMID 38693136, 2024). "In our finding, GSEA analysis revealed a correlation between CPT1A and the WNT/β-catenin signaling pathway in cervical cancer." (PMID 38693136, 2024). "To further evaluate the impact of metabolic pathways on metabolic modification in cervical cancer, we determined the mRNA transcription and protein expression of key enzymes related to sugar and lipid metabolism, namely, GSK3β, PKM2 and CPT1A." (PMID 31465717, 2020). "In vitro, we found CPT1A was upregulated in HSIL tissues and in cervical cancer cell lines." (PMID 42072286, 2026). "Lastly, upregulation of CPT1A partially reversed the suppression of WNT3A, β-catenin, and c-Myc protein expression mediated by TM7SF2-knockout, suggesting that TM7SF2 regulated the WNT/β-catenin signaling via CPT1A in cervical cancer cells." (PMID 38693136, 2024). "Notably, changes in CPT1A protein expression did not impact TM7SF2 protein expression level when CPT1A was overexpressed in cervical cancer cells, suggesting that CPT1A might function as a downstream effector of TM7SF2." (PMID 38693136, 2024).
COVID-19 (6 papers, 2021 to 2023). A disease caused by infection with severe acute respiratory syndrome coronavirus 2. "Finally, CPT1a has been associated with inflammasome activation, which has been observed in COVID-19 patients, and its role in fatty acid oxidation supports modulators of either fatty acid oxidation or inflammasome signaling as potentially novel therapeutic targets to mitigate disease." (PMID 33691089, 2021). "In another study, CPT1a+VDAC1+HLA-DR− M-MDSC frequencies were found to be significantly higher in severe compared to mild COVID-19 patients, and these differences were observed before the respiratory nadir in severe COVID-19 patients." (PMID 38257728, 2023). "Adding the percentage of VDAC1+CPT1a+ myeloid cells, pDCs, and H3K27Me3+VDAC1+CD4+ improved prediction of COVID-19 severity compared with basic clinical information, highlighting the important contribution of the immune cell populations identified to disease severity." (PMID 33691089, 2021).